PGR (progesterone receptor)
Diseases named in the same sentence as PGR in open-access papers (continued):
Sharing a sentence is not in itself a finding about the gene and the disease.
breast cancer (continued). "Tumors expressing PgR, but not ER (ER-/PgR+) are uncommon, comprising 2–8% of breast cancers, with less known about their characteristics and responsiveness to therapy." (PMID 26161666, 2015). "Triple-negative breast cancer (TNBC), accounting for 10%–20% of breast cancer, is characterized by the lack of estrogen receptor (ER), and progesterone receptor (PgR), and low expression of the receptor tyrosine kinase ErbB2 (also known as HER2/neu)." (PMID 25883211, 2015). "On the other hand, PA-MSHA has been shown to induce cytotoxic effects against estrogen receptor—and progesterone receptor–negative breast cancer cells lines and in breast cancer xenografts." (PMID 25768439, 2015). "Triple negative breast cancer (TNBC) represents 15–20 % of all breast cancers that lack estrogen receptor (ER) and progesterone receptor (PgR) expression as well as amplification of the human epidermal growth factor receptor 2 (HER2)." (PMID 26383236, 2015). "While most HR expressing breast cancers express the ER, a small minority express PgR but not ER, even after retesting." (PMID 26161666, 2015). "Many breast cancers, particularly those that do not express estrogen receptor, progesterone receptor, or high levels of HER2 (i.e., triple negative breast cancer (TNBC)) have high levels of expression of EGFR." (PMID 26143491, 2015). "The analysis of GC-MS data shows that the abundance of 13 VOCs changes between different breast cancer cell lines and is sensitive to the cell doubling time (CDT) and to the expression of specific prognostic factors such as Estrogen Receptor (ER), Progesterone Receptor (PgR) and HER2." (PMID 26304457, 2015). "Intrinsic molecular subtypes of breast cancer have been thoroughly studied, but previous research failed to assign the ER–/PgR+ phenotype to one specific and stable molecular subtype." (PMID 26437901, 2015). "Despite the success of tamoxifen since its introduction, about one-third of patients with estrogen (ER) and/or progesterone receptor (PgR) - positive breast cancer (BC) do not benefit from therapy." (PMID 25878567, 2015). "Although some pathological factors, including estrogen receptor (ER), progesterone receptor (PR) and c-erbB-2 (HER2), have been widely used as a reference in clinical diagnosis and treatment, their prognostic value for breast cancer still has certain limitations." (PMID 25116444, 2014). "In breast cancer, ERα/mTOR crosstalk is an important indicator of hormone receptor status, as IGF-mediated mTORC1 activation repressed progesterone receptor (PgR) expression in the ER+/PgR− breast cancer cell phenotype." (PMID 25283550, 2014). "In addition, we measured the expression of the estrogen receptor (ER), progesterone receptor (PR), and HER2/neu and the Ki-67 proliferation index to further assess the prognosis of breast cancer patients." (PMID 24879526, 2014). "Triple negative breast cancer (TNBC) is a heterogeneous subgroup of breast cancer characterized by the absence of expression of estrogen receptor (ER), progesterone receptor (PgR) and human epidermal growth factor receptor-2/neu (HER-2)." (PMID 25495193, 2014). "According to estrogen receptor (ER) and progesterone receptor (PR) status, breast cancer can be divided into two subgroups: hormone receptor positive and negative breast cancer." (PMID 25212775, 2014). "Although TAM has been successfully used in ERα-positive breast cancers, about 30% of patients are ERα- and/or progesterone receptor (PR)-negative and resistant to endocrine modification and therefore display poor prognosis." (PMID 24847310, 2014). "Triple negative breast cancers (TNBC), which lack the expression of the estrogen receptor (ER), progesterone receptor (PR), and human epidermal growth factor receptor 2 (HER2), account for more breast cancer-related deaths even though they represent only 15-25 % of total breast cancers." (PMID 25352949, 2014).
breast cancer (continued). "Age, tumour size, axillary lymph node status (nodal status), estrogen receptor (ER), progesterone receptor (PgR), histological grade and HER2, are widely accepted factors for the assessment of the prognosis and adjuvant treatment decision-making in breast cancer." (PMID 24567879, 2014). "We also found that the 555 patients with tumors with intermediate Ki-67 expression but negative or low PgR levels (<20%) had outcomes similar to those of patients with luminal B–like breast cancer." (PMID 24951027, 2014). "Triple-negative breast cancer (TNBC) is an aggressive type of breast cancer that does not express estrogen receptor (ER), progesterone receptor (PR), and human epidermal growth factor receptor (Her2/neu)." (PMID 24982892, 2014). "Triple negative breast cancer is characterized as being estrogen receptor, progesterone receptor and HER-2/neu receptor negative; it is a heterogeneous breast cancer subtype that is difficult to treat and is associated with high recurrence and poor outcome." (PMID 25495193, 2014). "Profiling by immunohistochemical assays using estrogen receptor (ER), progesterone receptor (PR), and human epidermal growth factor receptor 2 (HER2) classifies breast cancer into four phenotypically distinct subtypes: luminal A, luminal B, basal-like and HER2+ tumors." (PMID 25333260, 2014). "Expression of EGFR has been found in up to 80% of triple-negative (HER2/ER/PgR-negative) breast cancers, and targeting EGFR thus has also been viewed as a potential therapeutic strategy for such disease." (PMID 24707474, 2014). "This subtype of breast cancer accounts for 15-20% of all breast cancers and the signature of TNBCs is the lack of the estrogen receptor, progesterone receptor and the lack of the overexpression of HER2." (PMID 25260874, 2014). "We evaluated proliferation of MDA-MB-231, EGF-dependent breast cancer cells lacking estrogen and progesterone receptor expression as well as human EGF-receptor 2 (HER2) amplification (triple-negative)." (PMID 25373734, 2014). "A useful surrogate definition was developed to distinguish luminal A–like breast cancer from luminal B–like disease based on a combination of estrogen receptor (ER), progesterone receptor (PgR) and Ki-67 status, without a requirement for molecular diagnostics." (PMID 24951027, 2014). "A higher pCR rate was previously observed when breast cancer patients with ER- and PgR-negative tumors received NAC." (PMID 24527070, 2014). "On the other hand, mammary tumors with high levels of WT1 have a poor prognosis and high levels of WT1 expression are frequently observed in cases of breast cancer that are estrogen and progesterone receptor negative." (PMID 24955840, 2014). "Therefore, using IHC and FISH to detect the ER, PgR, HER2, and Ki67 status in CNB and subsequent OEB samples, we then constructed breast cancer molecular subtypes." (PMID 23957561, 2013). "In agreement with the largest meta-analyses of epidemiological studies to date, we did not observe an association for SHBG rs6259, PGR rs1042838, ESR1 rs2234693, CYP19 rs10046 and rs4775936, and UGT1A1 rs8175347 and breast cancer risk." (PMID 23935996, 2013). "Triple-negative breast cancer (TNBC) is a breast cancer subtype that is negative for estrogen receptor (ER) and progesterone receptor (PR) and epidermal growth factor receptor 2 (HER2)." (PMID 23593472, 2013). "Basal-like breast cancer is a heterogeneous disease characterized by the expression of basal cell markers, no estrogen or progesterone receptor expression and a lack of HER2 ov erexpression." (PMID 24171719, 2013). "This signature can identify progesterone receptor positive and negative patients for all 7 cohorts (1 meningioma and 6 breast cancer datasets), so it is robust enough for application to multiple cancer types." (PMID 24058887, 2013).
breast cancer (continued). "Histological work-up after mastectomy showed a grade 2 (pT1a, NX), oestrogen (+++) and progesterone receptor (+++) positive and Her2neu negative (Her2neu-[IH]) adenocarcinoma, indicating the presence of a distinct second breast cancer." (PMID 24596658, 2013). "Triple-negative breast cancers (TNBCs) constitute up to 20% of all breast cancers and are characterized by a lack of oestrogen receptor (ER) and progesterone receptor (PR), as well as human epidermal growth factor receptor 2 (HER2) amplification." (PMID 23601074, 2013). "We found loss of CLCA4 indicated lower relapse-free survival in basal breast cancers that were negative for both estrogen receptor and progesterone receptor and lymph-node positive." (PMID 24386311, 2013). "Our data showed that AT-MSCs did not increase the proliferation of the HER2-overexpressing, estrogen/progesterone receptor negative breast cancer cells SKBR3." (PMID 24209831, 2013). "The Iowa Women's Health study found a stronger protective effect of vitamin D supplement use among women with breast cancers that were negative rather than positive for estrogen receptor (ER) or progesterone receptor (PR) status." (PMID 23533810, 2013). "In vitro cell proliferation in normal and high glucose was measured by MTS assay in non-tumorigenic breast epithelial cells (MCF10A), estrogen/progesterone-receptor positive breast cancer cells (MCF7), and triple negative breast cancer cells (MDA-231)." (PMID 24260287, 2013). "Triple Negative Breast Cancer (TNBC) is a subtype of breast cancer that based on immunohistochemistry (IHC) is estrogens receptor (ER) negative, progesterone receptor (PR) negative and human epidermal growth factor receptor 2 (HER2) negative." (PMID 25285241, 2013). "Additionally, ER/PgR/HER2 were all triple-negative, possibly corresponding to basal-like type breast cancer." (PMID 23651662, 2013). "This subgroup of breast cancer is characterized by absent expression of estrogen receptor (ER), progesterone receptor (PR) and HER2 receptor and is defined as triple negative breast cancer." (PMID 24083544, 2013). "This is consistent with the role of high VRK2 level in breast cancer, in which also correlates with tumors having a better prognosis, those that are estrogen and progesterone receptor positive and ERBB2 negative." (PMID 24079673, 2013). "The 2011 St.Gallen breast cancer consensus also recommended that the IHC status of ER, PgR, HER2, and Ki67 could be used to approximately classify breast cancer into these subtypes, which can guide subsequent systemic treatment." (PMID 23957561, 2013). "Triple negative breast cancer (TNBC) defines a clinical subset of breast cancer negative for estrogen receptor (ER), progesterone receptor (PR) and human epidermal growth factor receptor type 2 (HER2)." (PMID 23825533, 2013). "The MMTV-PyMT transgenic mouse model is a widely used pre-clinical model of estrogen and progesterone receptor-negative luminal-like breast cancer with well-defined stages of progression and metastasis to lung." (PMID 23407024, 2013). "Metaplastic breast carcinomas are consistently negative for ER, PgR and Her-2/neu but positive for EGFR, as in nearly all of our cases." (PMID 24083491, 2013). "Triple-negative breast cancers lack estrogen receptor α (ERα), progesterone receptor, and do not overexpress human epidermal growth factor receptor 2 (Her-2)." (PMID 22290080, 2012). "Human breast cancer T47D cells, which are characterized as estrogen and progesterone receptor (ER/PR) positive and Her-2/neu (Her2) negative, were cultured in RPMI-1640 medium containing 10% FBS." (PMID 22134360, 2012). "TNBC is a subtype of breast cancer that overlaps with the basal-like breast cancers lacking estrogen receptor/progesterone receptor and HER2 expression." (PMID 22788954, 2012).
breast cancer (continued). "The diagnosis of breast cancer is confirmed by histological evaluation, and the tumor is assessed for grade as well as human epidermal growth factor receptor 2 (HER2), estrogen, and progesterone receptor status." (PMID 22295246, 2012). "In this study, breast cancer patients who were estrogen receptor negative (ER–) and progesterone receptor negative (PR–) were 39.2% and 44.2%, respectively." (PMID 22929014, 2012). "Basal type breast cancer is a subtype characterised by a lack of protein expression of oestrogen receptor (ER) and progesterone receptor (PR) and the absence of HER2 protein over expression." (PMID 23226290, 2012). "Basal-like breast cancer does not express estrogen receptor, progesterone receptor and HER2 (so called triple-negative breast cancer)." (PMID 23113927, 2012). "Breast cancers classified as “triple-negative” by clinical diagnostic markers (ESR1, PGR, and HER2 negative) are heterogeneous in their clinical behavior, morphology, and molecular biology." (PMID 23173005, 2012). "Whole-genome array profiling indicates that PyMT tumors most closely resemble the luminal B subtype of human breast cancer, although end-stage PyMT tumors are estrogen and progesterone receptor (ER and PR)-negative." (PMID 22225988, 2012). "Expression of progesterone receptor did not significantly influence BMFS in patients with breast cancer of the luminal subtype." (PMID 22233926, 2012). "Triple negative breast cancer (TNBC), which comprises approximately 15% of all breast carcinomas, is defined as breast carcinoma that does not express estrogen receptor (ER), progesterone receptor (PgR) or human epidermal growth factor receptor type 2 (HER2)." (PMID 22537901, 2012). "Our retrospective study showed no disease and overall survival differences between male and female breast cancer patients matched for year of diagnosis, age, tumor size, nodal stage, tumor grade, estrogen receptor, progesterone receptor and HER2 expression." (PMID 21816051, 2011). "In summary, the finding that ER/PgR-positive DCIS coexists in a minority of patients with ER/PgR-negative breast cancer, raises the issue of chemoprevention in this cohort of patients." (PMID 22091428, 2011). "Women who carry a BRCA1 mutation typically develop "triple-negative" breast cancers (TNBC), defined by the absence of estrogen receptor (ER), progesterone receptor and Her2/neu." (PMID 21396117, 2011). "In our study of ER/PgR-negativeinvasive breast cancer we found that in 8% of cases noncontiguousER/PR-positive DCIS was present." (PMID 22091428, 2011). "These analyses identified more frequent CT expression in estrogen and progesterone receptor negative breast cancer, including NY-ESO-1, LAGE-1, MAGEA, PAGE4 and SSX1." (PMID 21437249, 2011). "As opposed to female breast cancer the progesterone receptor expression in men was an independent prognostic factor in this study." (PMID 21816051, 2011). "Recent reports suggest increase in estrogen receptor (ER), progesterone receptor (PR) negative breast cancer yet little is known about histology or receptor status of breast cancer in Indian/Pakistani women.in the U.S." (PMID 20459777, 2010). "Positive reactions for both ER and PGR have been reported for lung cancer and give therefore no support to either breast cancer or metastasis diagnosis." (PMID 20565809, 2010). "Other variables including estrogen receptor (ER), progesterone receptor (PR), and epidermal growth factor receptor-2 (HER2) expression vary widely among breast cancer patients and thus are routinely assessed as a component of standard care for determining the most effective treatment." (PMID 21037853, 2010).
breast cancer (continued). "This indicated that the expression of ENPP2 in primary tumors of breast cancer patients was independent of the tumor size, grade, node, estrogen receptor (ER) and progesterone receptor (PgR) status." (PMID 20305819, 2010). "There was higher percentage of estrogen and progesterone receptor negative breast cancer (30.6% vs. 21.8%, p = 0.0095) breast cancer in Asian Indian/Pakistani women compared to Caucasians." (PMID 20459777, 2010). "Estrogen receptor (ER), progesterone receptor (PR) and human epidermal growth factor receptor-2 (HER2) are important and well-established prognostic and predictive biomarkers for breast cancers and routinely tested on patient’s tumor samples by immunohistochemical (IHC) study." (PMID 21221174, 2010). "About 10% to 15% of breast cancers do not express either estrogen and progesterone receptor and also do not overexpress/amplify the HER2-neu gene." (PMID 20630060, 2010). "Most breast cancers classified into the basal-like subtype have an estrogen receptor (ER)-negative, progesterone receptor (PgR)-negative and human epidermal growth factor receptor (HER) 2-negative (so-called "triple-negative") phenotype." (PMID 20959018, 2010). "We have also assessed the expression of other breast cancer biomarkers in our cohort (ER, HER2 and PgR and basal markers as defined by our group and others) and looked for the existence of correlations between the expression of the Vitamin D partners and these molecular markers." (PMID 20831823, 2010). "We observed a close correlation between nuclear YB-1 detection and absence of progesterone receptor expression (p = 0.002), indicating that nuclear YB-1 detection marks a specific subgroup of breast cancer." (PMID 19930682, 2009). "Features of hereditary breast cancer include an early age-of-onset and over-representation of the 'triple-negative' phenotype (negative for estrogen-receptor, progesterone-receptor and HER2)." (PMID 19298662, 2009). "Like in many other mouse mammary tumor models, K14-cre; ApcCKO/+ mammary tumors were negative for hormone receptors, Estrogen Receptor (ER) and Progesterone Receptor (data not shown)." (PMID 19197353, 2009). "Synchronous breast cancer also showed a higher likelihood of being negative for the progesterone receptor (P=0.08)." (PMID 19190627, 2009). "The aims of this study were to identify miRNA signatures that accurately predict the oestrogen receptor (ER), progesterone receptor (PR) and HER2/neu receptor status of breast cancer patients to provide insight into the regulation of breast cancer phenotypes and progression." (PMID 19432961, 2009). "Data on ER, PgR, and HER2 expression were used to classify breast carcinomas." (PMID 19758440, 2009). "This subgroup of breast cancers carries a better prognosis than estrogen/progesterone receptor negative patients, and they can often be treated with hormonal therapy alone." (PMID 18828924, 2008). "The objective in this study was to compare the levels of estrogen receptor-α (ER) and progesterone receptor (PR) in nonneoplastic breast epithelium between breast cancer cases and biopsy controls." (PMID 18466613, 2008). "Basal-like breast cancers are often called 'triple-negative' (TN) breast cancer, defined as estrogen receptor-negative, progesterone receptor-negative (i.e., HR-negative), and HER2-negative." (PMID 18947390, 2008). "Basal-type, or triple-negative, breast cancer (lacking estrogen receptor, progesterone receptor, and human epidermal growth factor receptor-2 expression) is a high-risk disease for which no molecular therapies are currently available." (PMID 19025652, 2008). "What sets these tumours apart is that unlike many breast cancers, basal-like tumours do not express the estrogen receptor (ER) or progesterone receptor (PR), nor do they have amplified HER2." (PMID 17875215, 2007).